FAM131C (family with sequence similarity 131 member C)
Synonyms: C1orf117; FLJ36766
Tractability: No criterion of Open Targets' tractability assessment is met for any kind of drug.
Gene: Protein-coding gene on chromosome 1 (16,057,769 to 16,073,651, reverse strand). Ensembl gene ENSG00000185519.
Subcellular location (Human Protein Atlas): Cytosol; Intermediate filaments; Nucleoli
Gene Ontology:
Molecular function: protein binding
Genetic constraint (gnomAD): Loss-of-function variants: 12 observed, 18.36 expected, observed/expected ratio (o/e) 0.65, 90% interval 0.42 to 1.06. The upper end of that interval is the gene's LOEUF score, 1.06, which puts it in group 4 of 6, group 1 being the genes least tolerant of losing a copy. Missense variants: 225 observed, 250.06 expected, observed/expected ratio (o/e) 0.9, 90% interval 0.81 to 1. Synonymous variants: 74 observed, 91.57 expected, observed/expected ratio (o/e) 0.81, 90% interval 0.67 to 0.98.
Homologues: Orthologues: macaque FAM131C (93% identical), pig FAM131C (84% identical), rat Fam131c (80% identical), mouse Fam131c (79% identical), guinea pig FAM131C (77% identical), rabbit FAM131C (77% identical), chimpanzee FAM131C (72% identical), dog FAM131C (67% identical), tropical clawed frog fam131c (50% identical), zebrafish fam131c (33% identical). Paralogues in human: FAM131A (32% identical), FAM131B (30% identical).